SMARCA5 (SNF2 related chromatin remodeling ATPase 5)
Description:
ATPase that possesses intrinsic ATP-dependent nucleosome-remodeling activity. Catalytic subunit of ISWI chromatin-remodeling complexes, which form ordered nucleosome arrays on chromatin and facilitate access to DNA during DNA-templated processes such as DNA replication, transcription, and repair; this may require intact histone H4 tails. Within the ISWI chromatin-remodeling complexes, slides edge- and center-positioned histone octamers away from their original location on the DNA template. Catalytic activity and histone octamer sliding propensity is regulated and determined by components of the ISWI chromatin-remodeling complexes. The BAZ1A/ACF1-, BAZ1B/WSTF-, BAZ2A/TIP5- and BAZ2B-containing ISWI chromatin-remodeling complexes regulate the spacing of nucleosomes along the chromatin and have the ability to slide mononucleosomes to the center of a DNA template in an ATP-dependent manner. The CECR2- and RSF1-containing ISWI chromatin-remodeling complexes do not have the ability to slide mononucleosomes to the center of a DNA template. Binds to core histones together with RSF1, and is required for the assembly of regular nucleosome arrays by the RSF-5 ISWI chromatin-remodeling complex. Involved in DNA replication and together with BAZ1A/ACF1 is required for replication of pericentric heterochromatin in S-phase. Probably plays a role in repression of RNA polymerase I dependent transcription of the rDNA locus, through the recruitment of the SIN3/HDAC1 corepressor complex to the rDNA promoter (By similarity). Essential component of the WICH-5 ISWI chromatin-remodeling complex (also called the WICH complex), a chromatin-remodeling complex that mobilizes nucleosomes and reconfigures irregular chromatin to a regular nucleosomal array structure. The WICH-5 ISWI chromatin-remodeling complex regulates the transcription of various genes, has a role in RNA polymerase I transcription (By similarity). Within the B-WICH complex has a role in RNA polymerase III transcription. Mediates the histone H2AX phosphorylation at 'Tyr-142', and is involved in the maintenance of chromatin structures during DNA replication processes (By similarity). Essential component of NoRC-5 ISWI chromatin-remodeling complex, a complex that mediates silencing of a fraction of rDNA by recruiting histone-modifying enzymes and DNA methyltransferases, leading to heterochromatin formation and transcriptional silencing (By similarity).
Synonyms: hSNF2H; SNF2H; WCRF135; hISWI; ISWI
Tractability: Small molecule: a structure with a bound ligand is known. PROTAC: UniProt records ubiquitination sites on it; ubiquitination databases record sites on it; its protein half-life has been measured.
Target class: Enzyme; Hydrolase
Gene: Protein-coding gene on chromosome 4 (143,513,445 to 143,557,486, forward strand). Ensembl gene ENSG00000153147.
Subcellular location: Nucleus; Chromosome
Subcellular location (Human Protein Atlas): Nucleoplasm; Nucleoli fibrillar center
Pathways (Reactome):
Gene expression (Transcription): B-WICH complex positively regulates rRNA expression; NoRC negatively regulates rRNA expression
Cell Cycle: Deposition of new CENPA-containing nucleosomes at the centromere
DNA Repair: Recruitment and ATM-mediated phosphorylation of repair and signaling proteins at DNA double strand breaks
Gene Ontology:
Molecular function: ATP binding; ATP hydrolysis activity; ATP-dependent chromatin remodeler activity; DNA binding; histone binding; histone octamer slider activity; protein binding; helicase activity; nucleosome binding; protein-RNA adaptor activity
Biological process: antiviral innate immune response; chromatin organization; chromatin remodeling; DNA repair; DNA-templated transcription initiation; negative regulation of mitotic chromosome condensation; nucleosome assembly; positive regulation of DNA replication; positive regulation of transcription by RNA polymerase III; regulation of DNA replication; regulation of DNA-templated transcription; DNA damage response; positive regulation of transcription by RNA polymerase I; positive regulation of transcription by RNA polymerase II; DNA methylation-dependent constitutive heterochromatin formation; heterochromatin formation; negative regulation of transcription by RNA polymerase I; rDNA heterochromatin formation
Cellular component: ACF complex; B-WICH complex; chromosome; condensed chromosome; fibrillar center; nuclear replication fork; nucleoplasm; nucleus; NURF complex; pericentric heterochromatin; RSF complex; site of double-strand break; WICH complex; CHRAC; nucleolus; CERF complex; chromatin silencing complex; ISWI-type complex; NoRC complex
Genetic constraint (gnomAD): Loss-of-function variants: 4 observed, 41.23 expected, observed/expected ratio (o/e) 0.097, 90% interval 0.047 to 0.22. The upper end of that interval is the gene's LOEUF score, 0.22, which puts it in group 1 of 6, group 1 being the genes least tolerant of losing a copy. Missense variants: 299 observed, 562.11 expected, observed/expected ratio (o/e) 0.53, 90% interval 0.48 to 0.58. Synonymous variants: 205 observed, 193.66 expected, observed/expected ratio (o/e) 1.06, 90% interval 0.94 to 1.19.
Gene-disease validity (ClinGen):
ClinGen rates the evidence that SMARCA5 causes each of these diseases.
complex neurodevelopmental disorder (autosomal dominant): Moderate. A disorder that involves more than one phenotype associated with the central nervous system, including but not limited to intellectual disability, autism, and seizures (epilepsy).
Homologues: Orthologues: chimpanzee SMARCA5 (99% identical), macaque SMARCA5 (99% identical), rabbit SMARCA5 (99% identical), dog SMARCA5 (99% identical), rat Smarca5 (98% identical), guinea pig SMARCA5 (98% identical), mouse Smarca5 (98% identical), pig SMARCA5 (93% identical), tropical clawed frog smarca5 (89% identical). Paralogues in human: SMARCA1 (81% identical), CHD2 (32% identical), CHD1 (30% identical), INO80 (28% identical), CHD7 (28% identical), HELLS (27% identical), CHD9 (27% identical), SRCAP (27% identical), SMARCA2 (27% identical), SMARCA4 (27% identical), CHD3 (26% identical), CHD5 (26% identical), and 18 more.
Diseases named in the same sentence as SMARCA5 in open-access papers:
SMARCA5 is named in the same sentence as 70 diseases in open-access papers, as found by Europe PMC text mining. Sharing a sentence is not in itself a finding about the gene and the disease. The quoted sentences say what the papers report.
breast cancer (28 papers, 2012 to 2025). A primary or metastatic malignant neoplasm involving the breast. "As for SMARCA5, it was an important chromatin remodeling gene and has been found associated with breast cancer, Alzheimer’s disease and leukemia." (PMID 30326835, 2018). "Other miRNAs recently implicated in breast cancer include miR-100, shown to target SMARCA5, SMARCD1, and BMPR2 genes, which directly influence tumor cell proliferation, and miR-30c, known to target TWF1 and IL-11, both of which are expressed in the MaSC/basal lineage." (PMID 26080807, 2015). "Another member of the ISWI subfamily implicated in breast cancer progression is the Remodeling and Spacing Factor (RSF) complex, which consists of a chaperone nuclear protein and SMARCA5 or SMARCA1." (PMID 41278204, 2025). "Overexpression of SMARCA5 is also frequently seen in breast cancer, which is positively correlated with the stages of tumor, node and metastasis, and poor overall survival." (PMID 41278204, 2025). "CircSMARCAS, generated through back-splicing of exons 15–16 of the SMARCA5 gene, is significantly downregulated in breast cancer tissues and cell lines, while its host gene SMARCA5 exhibits elevated expression." (PMID 41550639, 2025). "CircSMARCA5 terminates SMARCA5 transcription at exon 15 to reduce its expression, thereby inhibiting SMARCA5-mediated DNA damage repair and cisplatin resistance in breast cancer (BC)." (PMID 38044421, 2023). "SMARCA5, the other core ATPase subunit, is frequently overexpressed in various tumors, including in breast cancer, gastric cancer, acute myeloid leukemia (AML), and pancreatic ductal adenocarcinoma (PDAC)." (PMID 36361605, 2022). "CircSMARCA5 is negatively correlated with the expression of its parental gene SMARCA5 in breast cancer." (PMID 36231036, 2022). "Ectopic expression of circ-SMARCA5 (hsa_circ_0001445) was sufficient to render breast cancer cell lines sensitive to drugs, both in vitro and in vivo." (PMID 34771517, 2021). "In breast cancer, the SMARCA5 expression level is positively correlated with tumor size, TNM stage and poor overall survival." (PMID 34736517, 2021). "SMARCA5 is frequently overexpressed in breast cancer, ovarian cancer, HCC and acute myeloid leukemia (AML)." (PMID 34736517, 2021). "Another study demonstrated that, contrary to the SMARCA5 gene, circ-SMARCA5 (hsa_circ_0001445) is downregulated in clinical breast cancer samples compared to normal control tissues." (PMID 34771517, 2021). "E.g., downregulates circSMARCA5 in nuclear-induced chemoresistance of breast cancer by inhibiting the transcription of SMARCA5." (PMID 34635639, 2021). "Then we identified a circRNA derived from SMARCA5 (circSMARCA5) is significantly decreased in breast cancer cell lines and breast cancer samples." (PMID 32838810, 2020). "Compared to adjacent normal tissues, circSMARCA5 is decreased in breast cancer tissues, contrary to host gene SMARCA5." (PMID 32838810, 2020). "More importantly, we define a critical role for circSMARCA5 in the regulation of DNA damage repair capacity and the drug sensitivity of breast cancer cells in vitro and in vivo through the negative regulation of its parent gene SMARCA5." (PMID 32838810, 2020). "Additionally, circRNA molecules appear to negatively interact with the expression of host genes in breast cancer: the increased expression of circSMARCA5 lowered the expression of the SMARCA5 gene, consequently inhibiting DNA repair." (PMID 38339175, 2024). "Namely, the interaction of circSMARCA5 with SMARCA5 could suppress the expression of SMARCA5, which is vital for DNA damage repair, and altered DNA damage repair modulated the sensitivity of breast cancer cells to cytotoxic drugs." (PMID 35843942, 2022). "A study of breast cancer showed that miR-100 could induce the EMT process by regulating the expression of CDH1 (cadherin 1) through SMARCA5." (PMID 31885571, 2019).
breast cancer (continued). "Hence, a further study confirming their expression levels and functions in various subtypes of breast cancer is needed, as the balanced expression of SMARCA5 and SMARCA1 may be of interest for therapeutic purposes." (PMID 41278204, 2025). "Additionally, we identified the alterations of epigenetic targets, such as SWI/SNF related genes (SMARCA2, SMARCA4, SMARCA5) or histone modifiers (KMT2C or KMT2D), breast cancer-associated oncogenes (MYCN or MAPKs), or genes that are involved in drug-resistance (ESR1 and PIK3CA/B)." (PMID 31216647, 2019). "The direct targets of the miR-99 family are the chromatin remodeling factors SMARCA5, SMARCD1 and the growth regulatory kinase mTOR, which is also an important pathway activated in breast cancer." (PMID 22438871, 2012). "Due to its high stability, circRNA is an excellent biomarker for human diseases, especially cancer; examples include circ-SMARCA5 as a biomarker for hepatocellular carcinoma, circ-ANKS1B for breast cancer, circ-UBXN7 for bladder cancer and circ-LMTK2 for gastric cancer." (PMID 31631067, 2019).
prostate carcinoma (10 papers, 2013 to 2025). A carcinoma that arises from epithelial cells of the prostate gland. "Clinically, USP3 was significantly up-regulated in prostate cancer tissues and positively associated with SMARCA5 expression." (PMID 39500888, 2024). "However, the molecular mechanism underlying the regulation of SMARCA5 in prostate cancer remains largely elusive." (PMID 39500888, 2024). "Taken together, these results indicate that USP3 is upregulated in prostate cancer, positively correlating with SMARCA5 expression." (PMID 39500888, 2024). "Knockdown of USP3 impairs the DDR through SMARCA5 and results in increased sensitivity to Docetaxel treatment in prostate cancer cells." (PMID 39500888, 2024). "SMARCA5 (circSMARCA5) is involved in the occurrence of different cancers, but its role in prostate cancer carcinogenesis and metastatic transformation remains elusive." (PMID 34390329, 2021). "The role of SMARCA5 in cancer appears to be tissue type-specific, as the expression of SMARCA5 is upregulated in cervical and prostate cancers, whereas downregulation is reported in multiple myeloma, HCC, gastric cancer, intrahepatic cholangiocarcinoma, and non-small cell lung cancer." (PMID 40558499, 2025). "Moreover, a positive correlation between USP3 and SMARCA5 protein levels was observed in the prostate cancer human tissues supporting a role for the activity of the USP3-SMARCA5 axis in human prostate cancer cells." (PMID 39500888, 2024). "In addition, we found that USP3 expression is up-regulated in prostate cancer tissues and positively with SMARCA5 expression." (PMID 39500888, 2024). "SMARCA5 locates in the q31.1→q31.2 bands of chromosome 4 and is regarded as a critical contributor to malignant tumors, such as gastric cancer, acute leukemia and prostate cancer, among others, where SMARCA5 is significantly upregulated and shown to promote cancer progression." (PMID 32632040, 2020). "So we asked whether USP3 interacted with SMARCA5 to play function in prostate cancer." (PMID 39500888, 2024). "Moreover, USP3 knockdown sensitizes cancer cells to DNA-damaging agents in xenograft models, suggesting that the USP3- SMARCA5 axis may provide new therapeutic targets for overcoming chemotherapy resistance in prostate cancer." (PMID 39500888, 2024). "Previous studies have shown that QKI binds upstream and downstream of SMARCA5, ZEB1 and NDUFB2 RNA to promote circRNA formation in lung cancer, prostate cancer, and hepatocellular carcinoma." (PMID 40263288, 2025). "Our data perhaps suggest in RC43N, there is an 1α,25(OH)2D3-autoregulatory mechanism for BAZ1A/SMARCA5 expression and this function that is corrupted in RC43T, and AA prostate cancer." (PMID 37082578, 2023). "TCGA analyses identified a potential role for altered expression of the BAZ1A/SMARCA5 SWI/SNF complex, and this was replicated in another AA EA prostate cancer cohort." (PMID 37082578, 2023). "Herein, we report one critical target of USP3, SMARCA5 and the specific mechanism of USP3-mediated deubiquitination of SMARCA5 in Docetaxel-inducing DNA damage, suggesting that USP3 may be a promising target for anticancer therapy in prostate cancer." (PMID 39500888, 2024).
acute myeloid leukemia (8 papers, 2014 to 2024). Acute myeloid leukemia (AML) is a group of neoplasms arising from precursor cells committed to the myeloid cell-line differentiation. "Other studies have identified and characterized how the chromatin remodeling complex SMARCA5 mediates the abnormal chromatin accessibility in acute myeloid leukemia (AML) and revealed the important role of AKR1B1 in leukemia development." (PMID 39267837, 2024). "Upregulation of SMARCA5 was previously observed in CD34+ hematopoietic progenitors of acute myeloid leukemia (AML) patients." (PMID 32197313, 2020). "In this context, SMARCA5 regulates the access to DNA and is upregulated in acute myeloid leukemia, while TRIM71 is a post-transcriptional repressor involved in the cell cycle maintaining embryonic stem cell growth and in the processing of the presentation of class I MHC-mediated antigen." (PMID 35740429, 2022). "Moreover, Smarca5 is required for proliferation and/or differentiation of immature hematopoietic progenitors with extensive cytokine-induced proliferative capacity and is upregulated in acute myeloid leukemia (AML) blasts." (PMID 24498324, 2014). "A first-in-class inhibitor (ED2-AD101) of SMARCA5/CHD4 was recently shown to suppress cell growth in acute myeloid leukemia (AML) cells, but no inhibitors specifically targeting CHD4 are currently available for clinical use." (PMID 31921698, 2019).
gastric cancer (8 papers, 2019 to 2025). A primary or metastatic malignant neoplasm involving the stomach. "Smarca5 is deregulated in leukemia and breast, lung and gastric cancers." (PMID 35269430, 2022). "SMARCA5, an ATPase of the ISWI class of chromatin remodelers, is dysfunctional in leukemia and breast, lung, and gastric cancers." (PMID 35965507, 2022).
colorectal cancer (6 papers, 2011 to 2024). A primary or metastatic malignant neoplasm that affects the colon or rectum. "SMARCC1 is altered in prostate and colorectal cancer and SMARCA5 is known to be dysregulated in leukemia and up-regulated in human breast tumors." (PMID 21811619, 2011). "However, SMARCA1 was absent in the colon, according to protein expression data from the Human Protein Atlas (accessed 6/28/2024), underscoring the specific partnership between BAZ1A and SMARCA5 in colorectal cancer." (PMID 39112459, 2024). "Finally, we found that SMARCA5, MBD3, VPS53, EHD4 are estimated to mediate the regulation of miR-4701-3p and miR-4793-3p on colorectal cancer cell apoptosis, which targets ATP-dependent chromatin remodeling pathway and endocytic recycling pathway." (PMID 31998373, 2019).
glioblastoma (6 papers, 2020 to 2023). The most malignant astrocytic tumor (WHO grade IV). "A reduced SMARCA5 level was shown to correlate with anunfavorable prognosis in patients with glioblastoma.Overexpression of SMARCA5 contributes to reducedmigration of U87MG cells." (PMID 34707896, 2021). "The results showed that SMARCA5 is dramatically up-regulated in glioblastoma as compared to normal brain tissue." (PMID 32632040, 2020). "CircRNA SMARCA5 binds to SRSF1 protein to modulate VEGFA mRNA splicing in glioblastoma multiforme." (PMID 36800233, 2023). "Moreover, the TCGA dataset indicated that SMARCA5 expression in all four of the glioblastoma subtypes (classical, mesenchymal, neural, and proneural) was significantly higher than in normal controls." (PMID 32632040, 2020). "Additionally, current evidence shows that circRNA SMARCA5 (circ-SMARCA5) can bind to serine and arginine rich splicing factor 1 (SRSF1) to regulate VEGFA pathway in glioblastoma multiforme (GBM) cells." (PMID 31937318, 2020). "In glioblastoma multiforme, circ-SMARCA5 functions as a sponge for the splicing factor serine and arginine rich splicing factor 1 (SRSF1) (GBM)." (PMID 35883576, 2022).
leukemia (6 papers, 2011 to 2025). A malignant (clonal) hematologic disorder, involving hematopoietic stem cells and characterized by the presence of primitive or atypical myeloid or lymphoid cells in the bone marrow and the blood. "Smarca5 is frequently overexpressed in different cancer types, including glioma, leukemia, breast and gastric cancer." (PMID 35269430, 2022). "Thus, homeostatic expression of Smarca5 is very important for hematopoietic reconstitution, implicating a possibility that the Smarca5 role in AML cells might also involve a very early leukemia-initiating compartment." (PMID 32197313, 2020). "In normally differentiating myeloid cells both CTCF and SMARCA5 together with members of the Cohesin complex are recruited to the SPI1 gene, a key hematopoiesis regulator and leukemia suppressor." (PMID 24498324, 2014). "SMARCA5, through the interaction with CTCF in leukemic cells, actively inhibits expression of the SPI1/PU.1 gene that represents key hematopoietic transcription factor and dose-dependent leukemia suppressor." (PMID 32197313, 2020). "Thus in leukemia cells, AZA exposes newly hypomethylated sites to CTCF that together with SMARCA5 bind and control PU.1 expression." (PMID 24498324, 2014).